CDC42 (cell division cycle 42)
Diseases named in the same sentence as CDC42 in open-access papers (continued):
Sharing a sentence is not in itself a finding about the gene and the disease.
tumor (continued). "Although CDC42 was found to be upregulated in a variety of tumors, the loss of CDC42 in the liver leads to tumorigenesis and progressive development of HCC, suggesting a potential tumor suppressor role of CDC42." (PMID 36348464, 2022). "The significant role of Cdc42 in non-tumor diseases is also discussed." (PMID 35154449, 2022). "It is evident that high expression of CD47 promotes tumor invasion and metastasis through Cdc42, and the level of CD47 is associated with tumor stage and lymph node and distant metastasis, especially in NSCLC; therefore, CD47 can be used as a biomarker for the prognosis of NSCLC." (PMID 34367975, 2021). "delineated that Cdc42 could be rapidly and robustly activated by a pro-inflammatory factor Interleukin-6 (IL-6), thus mediating the IL-6 induced promotion of tumor growth and metastasis." (PMID 33726765, 2021). "Previous results revealed that GEFT–Rac1/Cdc42 accelerated tumor growth in mice." (PMID 34221974, 2021). "Moreover, RhoA and Rac1/Cdc42 activities, coordinated in regulating both membrane protrusions and cell matrix adhesions, have opposing effects on different modes of tumor cell motility." (PMID 33477952, 2021). "The notion that an amoeboid phenotype increases tumor cell invasion led us to believe that the mesenchymal‐to‐amoeboid transition of WM852 cells constitutes a compensatory mechanism in response to the reduced Cdc42‐dependent invasion of these cells." (PMID 33969605, 2021). "One study has suggested that Cdc42 may be a molecular regulator of the autophagy response to the tumor microenvironment." (PMID 34221974, 2021). "Together, CDC42 is proved to be involved in tumor promotion." (PMID 33406731, 2021). "Previous studies have reported M2 macrophage polarization suppressed PD-1 immunotherapy, which indicated that CDC42 expression may be closely related to the tolerance of tumor immunotherapy." (PMID 33380242, 2021). "Using TGT to study forces generated by tumor cells, it is found that highly tumorigenic tumor‐repopulating cells do not exhibit molecular force‐dependent cell spreading behavior due to severe downregulation of Cdc42." (PMID 33754478, 2021). "Collectively, these findings and published results support the conclusion that R-ketorolac preferentially targets Rac1 and Cdc42 which could account for the observed anti-tumor action." (PMID 33413202, 2021). "However, CD99 has both pro- and anti-tumour activity, and our data suggest that this results in part from its functional linkage to CDC42 and the diverse signalling pathways downstream of this Rho GTPase." (PMID 34374417, 2021). "The results showed that CDC42 expression was closely related to tumor immunity." (PMID 33380242, 2021). "Furthermore, CDC42 showed a strong correlation with the tumor infiltration levels of immune cells in HCC tissue." (PMID 33380242, 2021). "Importantly, the requirement for CDC42 activity in TEM and metastasis is linked to the CDC42-dependent induction of the ITGB1 gene, with β1 integrin playing a critical role in tumour cell intercalation into the endothelium." (PMID 34374417, 2021). "In addition, Rho protein family, consisting of Racl, Rho and Cdc42, can modulate cytoskeleton and cell adhesion, thereby playing an important role in promoting malignant transformation of cells as well as tumor invasion and metastasis." (PMID 32924971, 2020). "Moreover, we described in detail how VEGF also activates RhoA, Rac1, and Cdc42 contributing thus to tumor motility and invasion." (PMID 32377503, 2020). "PIK3 and CDC42 mediate a positive feedback loop to regulate the tumour progression role." (PMID 32445177, 2020). "Furthermore, consistent decrease at the transcriptomics level and in the urine peptide profiles was demonstrated for CD99, which is negatively regulating Cdc42 in tumour cells." (PMID 31900160, 2020).
tumor (continued). "Moreover, reduced Cdc42 expression was observed in tumor-infiltrating iNKT cells, which impaired IL4 polarization and disturbed iNKT cell-DC crosstalk in tumors." (PMID 31160756, 2020). "Together these data not only support the tumor suppressor function of AnxA6 but also suggest that the effector functions of RasGRF2, cell growth via Ras activation and inhibition of cell motility via Cdc42, are important in AnxA6 modulated tumor growth and cell motility." (PMID 30719209, 2019). "To test this we carried out GTPase activation assays to determine whether altered AnxA6 expression affected the effector functions of RasGRF2 i.e. activation of Ras proteins to promote tumor cell growth and inhibition of Cdc42 to inhibit tumor cell motility." (PMID 30719209, 2019). "Reactivation of CDC42 in the knock down cells is likely a major barrier to tumorigenesis and may account for the significant delay in tumor growth observed in these samples." (PMID 28460460, 2017). "Together, these data suggest that the cell polarity maintained by CDC42 might serve as an important barrier for bronchiolar tumor formation in lungs." (PMID 28871124, 2017). "LRP1B is a tumor suppressor and may regulate cell motility via the RhoA/Cdc42 pathway and actin cytoskeleton reorganization, but the exact role of LRP1B in HCC development has not been reported." (PMID 29117265, 2017). "Nuclear CDC42 expression showed significant negative associations with tumour grade (p < 0.001), tumour size (p < 0.001) and HER2 status (p = 0.018) but a positive correlation with ER status (p < 0.001)." (PMID 28451966, 2017). "First, we measured the protein expression levels of CDC42 in the tumor xenograft tissues." (PMID 28460460, 2017). "Thus, we propose a sub-population of CDC42 shRNA cells was able to re-express endogenous CDC42 leading to tumor growth." (PMID 28460460, 2017). "Interestingly, when compared to CDC42 shRNA cells before injection, CACNA2D2 expression was down-regulated in the CDC42 shRNA derived tumors to levels comparable to the parental CDC42-wt1 cell lines before injection and their corresponding tumor samples." (PMID 28460460, 2017). "CDC42 showed both nuclear and cytoplasmic staining in the invasive tumour cells." (PMID 28451966, 2017). "We hypothesised that CDC42 signalling could be useful in delineating a subgroup of Luminal A tumours with different phenotypic characteristics." (PMID 28451966, 2017). "Since CDC42 plays a central role in establishing and maintaining epithelial polarity which is frequently disrupted during tumor progression, we first analyzed the subcellular localization of a series of polarity proteins in Kras or Kras/Cdc42 bronchioles at three weeks post Ad-Cre treatment." (PMID 28871124, 2017). "High nuclear CDC42 staining was strongly correlated with the Luminal-type tumours (p < 0.001)." (PMID 28451966, 2017). "Therefore, the aim of this study was to investigate the effect of hypoxia on the expression of HIF-1α, RhoA, cdc42 and Rac1, RhoA activation, cell proliferation and migration using five tumor cell lines of different tissue origin." (PMID 28562340, 2017). "As CDC42 is important in cytoskeleton remodelling, it could be involved in contributing to the morphology of these tumours." (PMID 28451966, 2017). "It is also possible that some of these may be inactivating mutations, as in vivo evidence, such as deletion of Cdc42 from hepatocytes which lead to spontaneous tumor formation, suggests that Cdc42 might also play a role as a tumor suppressor." (PMID 27104658, 2016). "Taken together, these results suggest that tumor cells, stiffened by high levels of Cdc42 mediated actin polymerization, could limit their penetration out of vessels and through the ECM." (PMID 26787224, 2016). "Taken together, above results suggest that the role of PTBP1 in tumorigenesis may be partly mediated by its regulation of CDC42 alternative splicing and CDC42-v2 might function as a tumor suppressor." (PMID 26336992, 2015).
tumor (continued). "Our observation reported here suggests a hypothesis that the tumor promoting activities of CDC42 come from CDC42-v1 while the tumor suppressor activities come from CDC42-v2." (PMID 26336992, 2015). "Remarkably, inhibiting Cdc42 function impairs vessel co-option and converts pericytes to a phagocytic/macrophage-like phenotype, thus favoring an innate immune response against the tumor." (PMID 25032689, 2014). "Rac and Cdc42 counteract RhoA signalling pathways and promote tumour cell invasion." (PMID 24810913, 2014). "In pancreatic cancer, the overexpression of miR-143 significantly decreased the protein levels of MMP-2 and MMP-9, lowered the constitutive activities of RhoA, Rac1, and CDC42 GTPases, and also significantly inhibited cell migration and invasion of tumor cells in vivo and in vitro." (PMID 24670365, 2014). "Interestingly, hyperactivation of CDC42 can contribute to cellular transformation and tumor invasion and metastasis, through generation of plasma membrane protrusions, so-called invadopodia." (PMID 24498060, 2014). "Possible mechanisms for a role of CD151 overexpression in tumor progression may come from an enhancement of Rac and cdc42 activation and an effect of integrin-mediated tumor cell motility via FAK activation." (PMID 25285080, 2014). "Rho GTPases such as Rac, Cdc42 and RhoA are signaling proteins that regulate cytoskeleton organization, cell cycle progression, cell survival and migration directly contributing to tumor growth and progression." (PMID 24040362, 2013). "In addition, Cdc42 participates in intracellular trafficking and the regulation of malignant transformation, tumor progression and metastasis." (PMID 23538840, 2013). "Tumor cell migration is often associated with the occurrence of an epithelial-to-mesenchymal transition (EMT), and the activation of the small GTPases Rho, Cdc42 and Rac1." (PMID 23894465, 2013). "In addition, these studies revealed that Cdc42-mediated inhibition of c-Cbl plays an unexpectedly critical role in enabling tumour generation by BLBC cells." (PMID 23606532, 2013). "Reduction of c-Cbl expression abolished the effects of Cdc42 knockdown on tumour initiation." (PMID 23606532, 2013). "Future studies will be aimed at using this novel mouse model to determine the contribution of Cdc42 during different stages of tumor formation and progression and to define the molecular mechanisms by which aberrant Cdc42 expression facilitates these processes." (PMID 24074261, 2013). "Cdc42 knockdown cells formed significantly smaller tumours than cells expressing scrambled shRNA." (PMID 23606532, 2013). "Older women were characterised by a decreased expression of Cdc42 in the tumour blood vessels." (PMID 23420497, 2013). "Moreover, the decreased tumour size and prolonged survival seen in mice transplanted with 100,000 Cdc42 knockdown cells was dependent on restoration of c-Cbl function." (PMID 23606532, 2013). "Rho GTPases such as Cdc42 can also play an essential role in tumor cell migration." (PMID 24279335, 2013). "Furthermore, the low level of Cdc42 observed in the tumour stromal compartment was correlated with a postmenopausal status (P = 0.018)." (PMID 23420497, 2013). "Likewise, the small GTPase Cdc42 was shown to regulate actin filaments and the migration of tumor cells." (PMID 23984323, 2013). "Therefore, in order to directly and unambiguously address the role of Cdc42 in Ras-mediated transformation, tumor formation and maintenance, we have developed a model of conditional cdc42 gene in Ras-transformed cells." (PMID 22719838, 2012). "Whether and how Cdc42 and its related pathways contribute to Ras-mediated transformation and tumor maintenance in primary human pathologies will be an issue of further investigation." (PMID 22719838, 2012). "On the other hand, TGF-β can rapidly activate the Rho-family GTPases, Rac1, CDC42, and RhoA, in normal and tumor cells, although the mechanism is still unknown." (PMID 22614218, 2012).
tumor (continued). "Importantly, we uncovered a novel mechanism underlying LMP1-mediated Cdc42 activation, showing that LMP1 physically interacts with FGD4, leading to functional consequences associated with NPC tumorigenesis and tumor progression." (PMID 22589722, 2012). "Furthermore, additional studies are needed to assess the consequences and feasibility of targeting Cdc42 signaling in distinct tumorigenic and tumor maintenance contexts." (PMID 22719838, 2012). "Thereby, control of cell-cell contact to maintain cells as a cohesive epithelium and regulation of cell migration to favours invasion could be considered as two antagonistic effects of Cdc42 and Rac1 on tumour progression." (PMID 23144867, 2012). "Further, cdc42 targeting results in a substantial reduction in Ras-mediated tumorigenesis as well as a reduction in the growth of established tumors, suggesting that Cdc42 activation by oncogenic Ras is crucial for Ras-mediated tumorigenesis and tumor maintenance." (PMID 22719838, 2012). "The activity of Rho family GTPases such as Cdc42 may be up-regulated in tumor cells via increased protein expression or by increased activation from extracellular signals in the tumor environment (such as growth factors)." (PMID 21949762, 2011). "In addition to proliferation and apoptotic genes, we showed that genes related to tumor invasion, metastasis, and angiogenesis, such as MMPs and cdc42 are significantly downregulated post Ep-CAM silencing." (PMID 20461151, 2010). "Overall, TRAF7 alteration activates both tumor supportive (CDC42) and tumor suppressive (KLF4) pathways, and the co-occurrence of TRAF7 and KLF4 mutations allows for hyperactivation of Ras signaling as well as impaired tumor suppression, leading to meningioma growth." (PMID 41372821, 2025). "Based on current research findings, the FGD5 protein may regulate vascular pruning by participating in the VEGF (vascular endothelial growth factor) signaling pathway and activating the CDC42 protein, thereby modulating neovascular networks in both physiological conditions and tumor tissues." (PMID 41199744, 2025). "Furthermore, p120 downregulation may lead to tumor progression and metastasis by reducing β-catenin and E-cadherin expression, and altering the activities of Cdc42, Rac1 and RhoA." (PMID 39498333, 2024). "The reduced numbers of macrophages in the tumor may not only be due to impaired migration but to decreased macrophage differentiation since Rac and Cdc42 become activated during monocyte-macrophage differentiation; further studies are needed to demonstrate this." (PMID 37397366, 2023). "Cell division control protein 42 homolog (CDC42), GSTP1, and peptidyl-prolyl cis-trans isomerase A (PPIA) were associated with regulation of the stress-activated mitogen activated protein kinase (MAPK) cascade, which were closely related to the tumor cell proliferation." (PMID 37124724, 2023). "In addition, we revealed a novel role of eIF3a in tumor acquisition of invasive properties, including abundant pseudopodia formation and cytoskeleton reconstruction, by translationally regulating the expression of Cdc42 and RhoA." (PMID 35300416, 2022). "Thus, it is important to evaluate the spatial activation of intrinsic Rac1/Cdc42 in tumor tissues." (PMID 35110666, 2022). "Indeed, Cdc42 ablation in tumor cells suppresses progression of tumors." (PMID 33406731, 2021). "Finally, we investigated whether GEFT–Rac1/Cdc42 could inhibit tumor autophagy and apoptosis in vivo." (PMID 34221974, 2021). "The downregulated proteins were mainly associated with protein phosphorylation, CDC42 protein signal transduction, the receptor tyrosine kinase (RTK) signaling pathway, and focal adhesion assembly, all of which play essential roles in tumor growth and metastasis." (PMID 34623325, 2021).
tumor (continued). "Importantly, the spreading of tumour cells on ECs was inhibited by the depletion of CDC42, and the enhanced spreading of tumour cells seen upon CD99 depletion was also CDC42 dependent, with statistically significant differences in phenotype observed at the 4-h time point." (PMID 34374417, 2021). "Moreover, MEC-17-induced attenuation of cell migration was rescued after application of CASIN by the wound healing and Transwell assay, suggesting that MEC-17 determined cell morphology, migration and invasion ability, and tumour metastasis through ARHGAP21-mediated cdc42 activation." (PMID 30504808, 2018). "In addition, we found that DHA inhibited Cdc42-dependent tumor cell migration." (PMID 28506239, 2017). "Interestingly, cytoskeleton regulation via a specific member of Rho family – Cdc42 – was absent in the discrete groups of tumor cells and other structures and was associated only with solid structures." (PMID 28977854, 2017). "Although hypoxic conditions have been shown to increase tumor cell motility and aggressiveness through the activation of small GTPases, the cell-type dependence of the expression and activation of RhoA, cdc42 or Rac1 is unknown." (PMID 28562340, 2017). "Thus, high nuclear expression of CDC42 was strongly associated with tumours carrying good prognostic features such as low grade, non-ductal histology, ER positivity, HER2 negativity and smaller size." (PMID 28451966, 2017). "Therefore, antagonists that disrupt the binding of IQGAP1 to RAC1 and/or CDC42 could prevent tumor invasion, proliferation, and migration and could act as specific chemotherapeutic agents." (PMID 27815503, 2016). "Therefore, we tested whether Cdc42 may also be a downstream mediator of CD47-induced tumor invasion in NSCLC." (PMID 27411490, 2016). "Hence, ARHGAP10 may serve as a tumor suppressor through inactivating Cdc42, as well as inhibiting cell cycle, replication and BER pathways." (PMID 27010858, 2016). "Additionally, miR-206 was identified as tumor suppressor in breast cancer cell lines and was found to mediate this effect by directly targeting cell division cycle 42 (CDC42), resulting in down regulation of its protein expression together with that of MMP-2 and MMP-9." (PMID 24670365, 2014). "However, since both Cdc42 and Rac1 signaling contribute to cellular transformation and tumor progression, inhibition of several GTPases could prevent bypassing of the blocked pathways and might constitute a therapeutic advantage." (PMID 24040362, 2013). "Furthermore, an intriguing possibility is that Cdc42 overexpression may function during the early stages of tumor formation to induce protumorigenic and proinvasive stromal alterations." (PMID 24074261, 2013). "Moreover, disruption of Cdc42 function in established tumors inhibited continued tumor growth." (PMID 22719838, 2012). "Thus Cdc42 may lead to degradation of APC mutants and this may potentially increase the tumor susceptibility of the cells." (PMID 21311754, 2011). "Therefore, PLAG2A, E2F2 and CDC42 are the primary candidate tumor suppressors in this region." (PMID 16982006, 2006). "It promotes neuronal sprouting into the tumor microenvironment via pathways involving focal adhesion kinase (FAK) and Rho GTPases (Rac1, Cdc42), enhancing tumor growth and potentially contributing to cancer-related pain." (PMID 40243726, 2025). "Using human tumor cell-THP1 clusters at an optimized 1:4 ratio and anti-PLXNB2 antibody for co-immunoprecipitation, we also detected the enrichment of SEMA4A and CDC42 in the PLXNB2 protein complex, compared to monocytes only." (PMID 40818975, 2025).